KCNQ1 (potassium voltage-gated channel subfamily Q member 1)
Diseases named in the same sentence as KCNQ1 in open-access papers (continued):
Sharing a sentence is not in itself a finding about the gene and the disease.
atrial fibrillation (27 papers, 2008 to 2025). A disorder characterized by an electrocardiographic finding of a supraventricular arrhythmia characterized by the replacement of consistent P waves by rapid oscillations or fibrillatory waves that vary in size, shape and timing and are accompanied by an irregular ventricular response. "KCNQ1 G229D and R231C variants, located in the N-terminal half of S4, caused constitutively open IKs and were associated with atrial fibrillation and/or LQTS." (PMID 39100276, 2024). "Of note, the polymorphisms c.1394-39T>G in KCNQ1, one of the main genes associated with familial atrial fibrillation, was found linked to the presence of atrial fibrillation in ACM patients." (PMID 36008935, 2022). "Here, the authors trace the ancestry of a rare high impact atrial fibrillation allele in KCNQ1, and use iPSC-derived cardiomyocytes to characterize the effect of the allele." (PMID 34750360, 2021). "Two patients with atrial fibrillation due to gain-of-function mutations in KCNQ1 (R670K) and KCNE1 (G60D) were BMI-, age-, and sex-matched to six control participants and underwent a 6-h oral glucose tolerance test (OGTT)." (PMID 32164657, 2020). "Due to the critical role of IKs in heart rhythm regulation, unsurprisingly, many mutations in KCNQ1 and KCNEs have been functionally linked to life-threatening long and short QT syndromes as well as atrial fibrillation." (PMID 32581825, 2020). "The S140G gain-of-function KCNQ1 mutation, which is involved in IKs channels, induces atrial fibrillation." (PMID 30108508, 2018). "The KCNQ1 S140G mutation, which causes atrial fibrillation, is expressed in ventricular tissue and affects the IKs current, reducing the APD and ERP." (PMID 30108508, 2018). "The slow deactivation caused by two KCNQ1 atrial fibrillation mutations, S140G and V141M, is thought to play a key role in arrhythmogenesis by excessively increasing the repolarizing current of the cardiac action potential during repetitive stimulation." (PMID 28383569, 2017). "Two KCNQ1 gain-of-function mutations that cause a genetic form of atrial fibrillation, S140G and V141M, drastically slow IKs deactivation." (PMID 28383569, 2017). "The much rarer, genetic forms of atrial fibrillation have been associated with gain-of-function mutations in potassium channel subunits, such as two adjacent mutations in KCNQ1, S140G6 and V141M26." (PMID 28383569, 2017). "The KCNQ1 S140G mutation, which is involved in IKs current, affects atrial fibrillation." (PMID 30108508, 2018). "The KCNQ1 gene encodes the cardiac IKs channel, and it was the first disease gene linked to adult-onset familial atrial fibrillation (AF)." (PMID 41511320, 2025). "Paradoxically, gain-of-function mutations in KCNQ1 have been reported to cause borderline QT prolongation, atrial fibrillation (AF), sinus bradycardia, and sudden death, however, the mechanisms are not well understood." (PMID 30967788, 2019). "To date, eight gain-of-function mutations in KCNQ1 have been identified that underlie persistent familial atrial fibrillation (AF), and four have been reported to cause short QT syndrome type 2 (SQT2)." (PMID 30967788, 2019). "Gain-of-function (GOF) mutations supported by enhanced channel trafficking have also been reported for KCNQ1 in both inherited atrial fibrillation and short QT syndrome as well as for KCND3 in atrial fibrillation (AF)." (PMID 34572065, 2021). "Interestingly, IKs carrying the atrial fibrillation-linked mutation (AF) S140G in KCNQ1, has an increased Rb+ permeability compared with wild-type IKs." (PMID 32581825, 2020). "The changes in the IKs channels caused by the KCNQ1 S140G mutation in myocardial cells increase the current through IKs channels, reducing APD and ERP, and thereby inducing atrial fibrillation." (PMID 30108508, 2018).
atrial fibrillation (continued). "To study the gating effects of atrial fibrillation mutations using VCF, we employed a KCNQ1 construct containing a cysteine site at extracellular residue G219 that is close to S4 and can be labelled covalently with a fluorophore." (PMID 28383569, 2017). "The KCNE1-c.G112A (p.G38S) variant has been reported to reduce KCNH2 and KCNQ1 channel currents, enhance KCNH2 susceptibility to QT-prolonging factors, and increase the risk for LQTS, atrial fibrillation, and heart failure." (PMID 28749435, 2017). "Previously, in a Chinese family with atrial fibrillation and KCNQ1 mutation S140G, multiple family members had both LQTS and atrial fibrillation." (PMID 18400097, 2008). "Interestingly, KCNQ1:c.1394-39T>G and HCN4:c.1979-41A>G variants were found linked with atrial fibrillation in the patient and the fulfillment of depolarization abnormalities diagnostic criteria, respectively." (PMID 36008935, 2022). "Gain of function mutations in KCNQ1 can cause SQTS and atrial fibrillation." (PMID 22039467, 2011). "Gain-of-function mutations in either KCNQ1 or KCNE1 genes shorten the action potential duration and effective refractory period in cardiomyocytes, increasing the risk of atrial fibrillation (AF)." (PMID 32164657, 2020). "Atrial fibrillation (AF) and sinus bradycardia have been reported in patients with short QT syndrome variant 2 (SQT2), which is underlain by gain-of-function mutations in KCNQ1 encoding the α subunit of channels carrying slow delayed rectifier potassium current, IKs." (PMID 30337886, 2018). "Some atrial fibrillation (AF)-associated KCNQ1 and KCNE2 human gene variants augment KCNQ1-KCNE2 currents (which are typically much smaller in terms of outward current even than KCNQ1 alone) and would therefore be predicted to shorten the atrial action potential, thought to predispose to AF." (PMID 24478792, 2014).
deafness (26 papers, 2008 to 2025). An inherited or acquired condition characterized by the complete loss of the ability to hear from one or both ears. "Variants linked to JLNS (homozygous or compound heterozygous KCNQ1 variants linked to QT prolongation and deafness) in the literature clustered within the loss-of-function range, with 83% (34/41) showing partial loss or loss-of-function in the MAVE assay." (PMID 41445606, 2025). "Homozygous mutations or compound heterozygous mutations in KCNQ1 can lead to Jervell and Lange–Nielsen syndrome, which is characterized by decreased inner ear IKs and deafness." (PMID 35765105, 2022). "Null mutations in either Kcne1 or Kcnq1 disrupt endolymph production and K+ circulation in the inner ear, causing deafness and vestibular dysfunction." (PMID 33514733, 2021). "In mouse, mutations in genes expressed by marginal cells of the SV, including Slc12a2, Atp1b2, Kcnq1, and Kcne1, result in a loss or reduction of EP and deafness." (PMID 34566577, 2021). "Next, we need to conduct experiments to verify the dysfunction of Kv7.1 induced by KCNQ1 gene mutations and explore the mechanism of deafness." (PMID 32508908, 2020). "Three families of JLNS who presented with long QT and deafness and who carry homozygous, or compound heterozygous mutation in KCNQ1 gene were presented in this report." (PMID 29037160, 2017). "Complete absence of IKs in individuals with homozygous or compound heterozygous pathogenic variants in KCNQ1 leads to LQTS combined with deafness (Jervell-Lange-Nielsen syndrome), while individuals harboring heterozygous pathogenic variants in KCNQ1 display LQTS with normal hearing." (PMID 36721196, 2023). "In addition, we identified potentially novel deafness-associated genes Mpzl2 in IMCs and Tbx1 in MCs along with the known deafness-associated genes in IMCs (Kcnj10, Met, Mitf, Gjb6, Ednrb, and Gjb2) and in MCs (Kcnq1, Esrrb, Kcne1, Lrp2, Slc22a4, and Hgf)." (PMID 37322474, 2023). "Mutations in KCNQ1/KCNE1 result in human deafness and have been reviewed previously." (PMID 34566577, 2021). "Importantly, transepithelial potassium transport in the inner ear is also associated with the KCNQ1 protein, which is why KCNQ1 variants may cause deafness in JLNS1." (PMID 28595573, 2017). "Two of these genes (KCNQ1 and KCNE1) also cause the rare autosomal recessive form of Jervell Lange-Nielsen Syndrome (JLNS1-2), associated with deafness 3–5." (PMID 39788950, 2025). "Studies have shown that cochleostomy injection of AAV1 containing Kcnq1 into Kcnq1 knockout mice resulted in significant hearing restoration, ranging from a 20 dB improvement to a complete correction of the deafness phenotype." (PMID 38327848, 2024). "KCNQ1 knockout mice presented symptoms such as deafness, balance problems, and morphological anomalies in the internal ear and in the gastrointestinal tract." (PMID 33498651, 2021). "For instance, KCNE1- or KCNQ1-null mice show severe collapse of the scala media and deafness, implying that KCNQ1/KCNE1 K+ channels are crucial for driving K+ transport and maintaining the endolymph." (PMID 27568193, 2016). "In this report, we describe a Chinese family in which a heterozygous mutation in KCNQ1, T322M, resulted in RWS whereas the homozygous mutation resulted in JLNS associated with LQTS and deafness." (PMID 18400097, 2008). "Indeed, gross morphological anomalies in inner ear structures and severe histological alterations of the gastric mucosa, accompanied by deafness and impaired acid secretion, respectively, have been reported using KCNQ1-KO mice models." (PMID 36699692, 2022). "With respect to the severity of the cardiac phenotype and the occurrence of deafness, the phenotypic expression of CACNA1D mutations resembles the phenotypic spectrum seen in loss-of-function mutations in the KCNQ1 gene encoding the α1-subunit of the cardiac potassium channel Kv7.1." (PMID 36430690, 2022).
deafness (continued). "Using deafness panel sequencing, we excluded KCNE1 gene mutation which was identified as the cause of JLNS and found a novel compound heterozygous mutation c.1741A>T/c.477+5G>A in KCNQ1 gene of proband 1-II-1." (PMID 32508908, 2020). "Occasionally, bi‐allelic mutations in KCNQ1 are also found in patients without any deafness, referred to as autosomal recessive long QT syndrome, type 1 (AR LQT1)." (PMID 28944242, 2017). "Homozygous gene variants in KCNQ1, or compound heterozygous gene variants, may cause the recessive JLNS variant, which is characterized by deafness." (PMID 28595573, 2017). "MinK knock-out mice display inner ear defects with deafness similar to what is observed in patients with JLNS, again highlighting the relevance of the KCNQ1/KCNE1 channel complex in the inner ear." (PMID 33498651, 2021).
epilepsy (24 papers, 2014 to 2026). A brain disorder characterized by episodes of abnormally increased neuronal discharge resulting in transient episodes of sensory or motor neurological dysfunction, or psychic dysfunction. "The association of the KCNQ1 Q234K variant and epileptiform activity (or epilepsy) remains a matter of speculation." (PMID 39100276, 2024). "On the other hand, there have been several reports that KCNQ1 variants may also be associated with epilepsy as a brain/cerebral phenotype." (PMID 39100276, 2024). "The data strongly support emerging concepts that KCNQ1 mutations may increase the risk of epilepsy, but additional genetic modifiers are necessary for the clinical manifestation of epileptic seizures." (PMID 31293497, 2019). "Indeed, genetic analyses conducted in SUDEP cases have revealed the presence of potentially dangerous genetic alterations in genes involved in the control of cardiac rhythm (such as KCNQ1) and in genes associated with severe forms of epilepsy (such as SCN1A and DEPDC5)." (PMID 41062843, 2026). "Moreover, genetic variants in the KCNQ1 gene were reported in three cases of sudden unexpected death in epilepsy (SUDEP), a catastrophic complication of human idiopathic epilepsy with unknown causes." (PMID 27064559, 2016). "Genes such as SCN5A, KCNQ1, KCNH2, RYR2 are associated with both channelopathies and epilepsy and almost 40% of people with LQT2 and 20% of those with LQT1 present an epileptic phenotype." (PMID 41062843, 2026). "The most prevalent types of LQTS are caused by mutations in three cardiac channels: KCNQ1, KCNH2 and SCN5A, which have been also associated with epilepsy and sudden unexpected death in epilepsy (SUDEP)." (PMID 33375447, 2020). "For KCNQ1 mutation carriers, only one small family having both, LQT syndrome and epilepsy, has been characterized in detail." (PMID 31293497, 2019). "Both KCNQ1 and KCNE1 are reported to be expressed in the brain, where KCNQ1 interacts with KCNE1, and there have been several reports that KCNQ1 variants are associated with both LQTS and epilepsy." (PMID 39100276, 2024). "While the exon 2 deletion in KCNQ1 showed complete segregation with the LQTS, it is unlikely that the CDKL5 variant was causative of the observed epilepsy, as mutations related to this gene typically occur de novo and are associated with early-onset, severe, drug-refractory epileptic encephalopathy." (PMID 29261713, 2017). "The KCNQ1 Q234K induced IKs gain-of-function during long (8-s)-depolarization, while loss of-function during short (400-ms)-depolarization, which indicates that the variant causes LQTS, and raises a possibility that the variant may also cause epilepsy." (PMID 39100276, 2024). "The evidence that KCNQ1 genetic variations may confer susceptibility for recurrent seizure activity increasing the risk of sudden death is further supported by the description of a pathogenic KCNQ1 variant (p.Leu273Phe) in a family featuring LQTS and epilepsy." (PMID 27064559, 2016). "Indeed, mutations of KCNQ1, KCNE1, and SCN5A could also be found in certain epilepsy patients." (PMID 32848785, 2020). "Patients with a prior epilepsy diagnosis constituted 5 of 19 for LQTS probands (3 KCNH2 and 1 KCNQ1), 2 of 15 for CPVT probands (1 RYR2), and 1 of 15 for BS probands (1 SCN5A)." (PMID 32298319, 2020). "KCNQ1 and KCNQ4 are expressed in multiple tissues (KCNQ4 in the auditory system and vasculature, KCNQ1 in the cardiovascular system and multiple epithelia) and their activation might cause unwanted off-target effects if one were instead intending to target KCNQ2 in epilepsy, for example." (PMID 31701029, 2019). "As opposed to KCNQ1, which is predominantly expressed in the adrenal glands and the thyroid, KCND2 is most expressed in brain tissue; KCND2 genetic variants have been associated with both epilepsy and autism." (PMID 30458022, 2018).
Jervell and Lange-Nielsen syndrome (24 papers, 2008 to 2026). "We describe the identification of nine Belgian families with a pathogenic frameshift variant in KCNQ1, with initial presentation as Jervell-Lange-Nielsen syndrome in two siblings and LQTS in the remaining 8 families." (PMID 36721196, 2023). "KCNQ1 is associated with Jervell and Lange-Nielsen syndrome (JLNS, OMIM# 220400), which is characterized by profound congenital hearing loss and a prolonged QTc interval in the electrocardiography waveforms." (PMID 35761346, 2022). "Jervell and Lange-Nielsen syndrome is caused by homozygous or compound heterozygous mutations in KCNQ1 on 11p15.5 or KCNE1 on 1q22.1-q22.2." (PMID 28364778, 2017). "The R518X/KCNQ1 mutation is a common cause of autosomal recessive (Jervell and Lange Nielsen Syndrome- JLNS) and autosomal dominant long QT syndrome (LQTS) worldwide." (PMID 24552659, 2014). "Subject B, a 3-year-old girl with congenital deafness and a QTc of 580 ms, was diagnosed with Jervell and Lange-Nielsen syndrome (JLNS), harboring a homozygous KCNQ1 p.Arg192Cys variant." (PMID 41768584, 2026). "As an example, both PTCs and missense variants leading to LoF of KCNQ1 are associated with LQTS and Jervell Lange-Nielsen syndrome." (PMID 37872640, 2023). "Jervell and Lange-Nielsen syndrome (JLNS) is a rare autosomal recessive LQTS form, caused by KCNQ1 variants." (PMID 36674868, 2023). "KCNE1 also regulates KCNQ1 in the inner ear, which is why some individuals harboring loss-of-function mutants in KCNQ1 or KCNE1 in both alleles succumb to Jervell and Lange-Nielsen Syndrome (JLNS), comprising both LQTS and sensorineural deafness." (PMID 24478792, 2014).
channelopathies (23 papers, 2012 to 2026). "Our gene-based meta-analyses identified a burden of rare coding variants associated with QT, JT, and QRS, in genes typically linked with inherited channelopathies (KCNQ1, KCNH2) and cardiomyopathies (MYH7, TNNI3K)." (PMID 36050321, 2022). "Our data causally link impaired Ca2+ sensitivity of the KCNQ1 mutants to postnatal growth retardation and/or gingival overgrowth, characterizing a particular KCNQ1 channelopathy." (PMID 36077086, 2022). "Our data link impaired Ca2+ sensitivity of the KCNQ1 mutants R116L, V185M and P369L to Q1E2 gain-of-function that is associated with a particular KCNQ1 channelopathy." (PMID 36077086, 2022). "Gingival overgrowth is not only found in individuals with the KCNQ1 variants R116L and P369L, but also in individuals with another subgroup of channelopathies caused by K+ channel gain-of-function." (PMID 36077086, 2022). "It is possible that attenuated β-blocker efficacy is RyR2 mutation-specific, as KCNQ1 mutation-specific responses to β-blocker therapy have been observed in type I long QT syndrome, another inherited arrhythmogenic channelopathy." (PMID 27491078, 2016). "In particular, variants within the KCNQ gene family (KCNQ1–5, also referred to as Kv7.1–5) have figured prominently in human channelopathies." (PMID 23781230, 2013). "Indeed, it is usually performed in cases of research projects, performing the analysis of the most prevalent genes associated with channelopathies (such as KCNQ1, KCNH2, SCN5A, and others), excluding other important candidate genes." (PMID 34356248, 2021). "Channelopathies, such as mutations in the HCN4, SCN5A and KCNQ1 genes, which encode ion currents If, INa and IKs, can lead to reduced pacemaker rate." (PMID 34814734, 2021). "This is highlighted in cases in which an altered regulation of ion channels by PIP2 leads to channelopathies, as observed for KCNQ1." (PMID 22787448, 2012). "The channelopathies are associated with the following genes: SCN5A, KCNQ1, KCNH2, KCNE1, RYR2." (PMID 38793126, 2024). "When the autopsy does not show any structuralcardiac anomaly, channelopathies he following panel of genes: SCN5A, KCNQ1, KCNH2, KCNE1, and RYR2 should be used." (PMID 38793126, 2024).
Brugada syndrome (19 papers, 2014 to 2025). A genetically heterogeneous condition characterized by complete or incomplete right bundle branch block accompanied by ST elevation in leads V1-V3. "Variants in KCNQ1 (NM_000218.2) or KCNH2 (NM_000238.3) responsible for Romano-Ward long-QT syndrome types 1, 2, and 3 and for Brugada syndrome, were observed in 4 individuals." (PMID 32231684, 2020). "Rare variants in the cardiac potassium channel KV7.1 (KCNQ1) and sodium channel NaV1.5 (SCN5A) are implicated in genetic disorders of heart rhythm, including congenital long QT and Brugada syndromes (LQTS, BrS), but also occur in reference populations." (PMID 30828412, 2019). "One KCNQ1 c.1124_1127delTTCA harboring patient was diagnosed with Brugada syndrome (BrS)." (PMID 36721196, 2023).